MCPH1 (microcephalin 1)
Diseases named in the same sentence as MCPH1 in open-access papers (continued):
Sharing a sentence is not in itself a finding about the gene and the disease.
breast carcinoma (continued). "Many studies have reported that the expression level of the MCPH1/BRIT1 gene is decreased in different types of cancers including lung cancer, cervical cancer, breast cancer, prostate cancer and ovarian cancer when compared with normal tissues." (PMID 36845691, 2023). "Decreased MCPH1/BRIT1 protein and RNA expression levels, and/or deletions and inactivation due to methylation were reported in 96% (121/126) of breast cancer cases." (PMID 36845691, 2023). "Ectopic expression of MCPH1 through genetic approaches effectively suppressed breast cancer cell proliferation and colony formation in vitro and tumor growth in vivo." (PMID 32121580, 2020). "The current genetic data brings now firm evidence for the role of MCPH1 in breast cancer prevention." (PMID 26820313, 2016). "The association with breast cancer was replicated with the unselected breast cancer cohort, where 16 additional MCPH1 c.904_916del carriers were identified (16/1150, 1.4%, P = 0.016, OR 3.3, 95% CI 1.2–8.9)." (PMID 26820313, 2016). "The genetic data combined with the evidence of genomic instability related to identified MCPH1 mutation and also loss of the other functional gene copy in several mutation carrier tumors establish MCHP1 as a novel breast cancer susceptibility gene." (PMID 26820313, 2016). "Although MCPH1 resides in chromosomal region 8p23.1, frequently found aberrated in different malignancies including lung, ovarian and breast cancer, only one of the studied tumors had lost the mutant allele." (PMID 26820313, 2016). "Low levels of MCPH1 were found in chronic myeloid leukemia cells, correlates with survival in ovarian cancer and is a prognostic indicator in breast cancer." (PMID 25148247, 2014). "Further, MCPH1 was found to be downregulated at the transcript level in 19/30 ovarian cancer specimens and at the protein level in 93/319 breast cancer tissues." (PMID 23472065, 2013). "Copy number and expression of MCPH1 were reduced in 35 of 87 (40%) advanced epithelial ovarian tumors and in 72% of 54 breast cancer specimens." (PMID 20169082, 2010). "Among these concordantly methylated genes, several have known tumor-suppressive activities in PCa, including ERBB4, MCPH1, RBMS3, and AKAP12, High DNA methylation levels of ERBB4 have been associated with poor prognosis and aggressive disease in breast cancer patients." (PMID 40723280, 2025). "Case 4 with breast cancer at the age of 48 years had CHEK2 c.1100delC and MCPH1 c.909_921del alleles, and her father, diagnosed with prostate cancer (age unknown) and lung cancer (84 years), was also identified as a double carrier." (PMID 40009290, 2025). "MCPH1/BRIT1 has also been identified as a novel hereditary breast cancer gene." (PMID 36845691, 2023). "Furthermore, the overexpression of MCPH1/BRIT1 in the MCF7 breast cancer cell line suppressed proliferation both in vivo and in vitro." (PMID 36845691, 2023). "The importance of MCPH1 for prevention of malignancy, particularly in breast epithelial cells, has been indicated by previous studies reporting somatic MCPH1 downregulation in multiple breast cancer cell lines and breast cancer specimens." (PMID 26820313, 2016). "For some genes, single P/LP variants were detected either only in the group of patients with breast cancer (APC, MDM1, MRE11, POLD1, NF1, RAD51C, RECQL4, and WRN) or only in the control group (MCPH1, MSH3, and XPC)." (PMID 39684352, 2024). "The expression level of the MCPH1/BRIT1 gene is decreased at the DNA, RNA or protein level in a number of types of cancers including breast cancer, lung cancer, cervical cancer, prostate cancer and ovarian cancer compared to normal tissue." (PMID 36845691, 2023).
breast carcinoma (continued). "Given the numerous functions of MCPH1 in DNA damage response, we determined the impact of c.904_916del to genomic stability assessed by chromosomal analysis in non-transformed peripheral blood lymphocytes of 7 mutation carriers negative for other known breast cancer associated mutations." (PMID 26820313, 2016). "For example, the β-deletion has been shown or speculated to be regulated by RMB10 in pancreatic cancer; NOVA1/PTBP1 in lung cancer; SRSF11, hnRNPH2, and hnRNPL in breast cancer; and MCPH1/BRIT1 in ovarian cancer." (PMID 33924498, 2021). "Decreased MCPH1 protein levels are associated with triple negative breast cancers and a lower transcript level of MCPH1 correlates with lesser time for metastasis in breast cancer." (PMID 23472065, 2013). "The targeted next-generation sequencing revealed a recurrent deletion in the MCPH1 gene (also known as BRIT1, NM_024596.3: c.904_916del, rs747489687) in 3/189 of the analyzed patients, these carriers being negative for any other known breast cancer associated gene mutations." (PMID 26820313, 2016). "Moreover, while the exogenous expression of an RNAi-resistant full length MCPH1-transcript was sufficient to rescue this effect of the MCPH1 knockdown, a transcript that was isolated in a human breast cancer specimen lacking the C-terminal BRCT-domains was not able to complement the defect." (PMID 20169082, 2010).
autosomal recessive primary microcephaly (11 papers, 2014 to 2024). Autosomal recessive primary microcephaly (MCPH) is a rare genetically heterogeneous disorder of neurogenic brain development characterized by reduced head circumference at birth with no gross anomalies of brain architecture and variable degrees of intellectual impairment. "Mutations in a number of identified genes have been found to underlie autosomal recessive primary microcephaly (MCPH) (e.g., MCPH1, ASPM, CASC5, and WDR62) and thanatophoric dysplasia (FGFR3), a subtype of megalencephaly." (PMID 31338027, 2019). "So far, five genes associated with autosomal recessive primary microcephaly (MCPH) have been identified in patients: MCPH1, CDK5RAP2, ASPM, CENPJ, and STIL/SIL." (PMID 28933765, 2017). "Human autosomal recessive primary microcephaly (MCPH) is a heterogeneous disorder with mutations in twelve genetic loci (MCPH1–12)." (PMID 29058117, 2017). "Human MCPH1 (hMCPH1) is a causative gene of autosomal recessive primary microcephaly (MCPH), a neurodevelopment disorder characterized by reduced brain size." (PMID 24972868, 2014). "Mcph1 (microcephaly, primary autosomal recessive 1; REC-N = 39.05) was the most controlled gene in “N”, while Usp31 (ubiquitin specific peptidase 31, REC-L = 27.93) and Syt11 (synaptotagmin XI, REC-L = 26.25) were the most controlled genes in “L”." (PMID 38534766, 2024). "Homozygous mutations and deletions of the microcephalin gene (MCPH1; OMIM *607117) have been identified as a cause of autosomal recessive primary microcephaly and intellectual disability (MIM #251200)." (PMID 28878824, 2017). "Exome analysis also showed heterozygous variants in three genes, ATR, MCPH1 and BLM, which are known causes of autosomal recessive primary microcephaly." (PMID 28464862, 2017). "In this context, causative genes of human autosomal recessive primary microcephaly, such as ASPM and MCPH1, are attractive candidates, as many of them show positive selection during primate evolution." (PMID 25870538, 2015).
lung cancer (8 papers, 2016 to 2025). A malignant neoplasm involving the lung. "Functional studies were also performed in A549 lung cancer cells, which demonstrated over-expression of MCPH1/BRIT1 caused reduced proliferation due to cell-cycle arrest at S and G2/M and increased apoptosis." (PMID 36845691, 2023). "Of the uniquely gained genes, MCPH1 (microcephalin) is notable as a key regulator of DNA damage response and a repressor of human telomerase reverse transcriptase function, and gains of MCPH1 have been implicated in increased platinum sensitivity in nonsmall cell lung cancer." (PMID 31137920, 2019). "In the lung cancer samples significant lower numbers of MCPH1/BRIT1-positive cells were identified compared with normal tissues." (PMID 36845691, 2023). "Three lung cancer studies related to MCPH1/BRIT1 were identified, all of which were conducted in Chongqing, China." (PMID 36845691, 2023). "A small follow up study confirmed significantly reduced MCPH1/BRIT1 mRNA expression in lung cancer samples compared to adjacent normal tissue." (PMID 36845691, 2023). "In recent years, MCPH1 mutations have been observed in breast, ovarian, prostate, and lung cancers, highlighting a link between MCPH1 dysfunction and tumorigenesis." (PMID 33203878, 2020). "The relatives of MCPH1 c.904_916del carriers were also reported to have several other types of malignancies, the most common being lung cancer, which occurred altogether in 38% (8/21) of all carrier families." (PMID 26820313, 2016). "Interestingly, a study has shown that overexpression of MCPH1 inhibits the migration and invasion of lung cancer cells by regulating proteins that control epithelia-mesenchymal transitions, among them p5355." (PMID 39885205, 2025). "In line with this, 2/4 studied non-breast tumors (lung carcinoma and liver metastasis from gastric adenocarcinoma) of MCPH1 c.904_916del carriers had lost the wild-type allele." (PMID 26820313, 2016). "MCPH1 alterations have also been reported in TCGA datasets retrieved from cBioPortal Cancer Genomics database, not only in breast tumors (about 7%) but also in other malignancy types observed in the currently identified carrier families (sarcomas 3.5%, brain tumors 1% and lung cancer 8%)." (PMID 26820313, 2016). "The initial study used immunohistochemistry to evaluate the expression of MCPH1/BRIT1 protein in two groups, 188 patients with lung cancer and 20 patients with normal lung tissues." (PMID 36845691, 2023).
ovarian carcinoma (8 papers, 2010 to 2023). A malignant neoplasm originating from the surface ovarian epithelium. "In support of inherited susceptibility to the disease, 44% (7/16) of the 16 MCPH1 mutation carriers from the unselected cohort also had at least one breast and/or ovarian cancer case among their 1st and 2nd degree relatives." (PMID 26820313, 2016). "According to a prior study, MCPH1/BRIT1 acts as a negative regulator of the functional variant α+/β+ hTERT in ovarian cancer, while, the α-/β+ hTERT and α-/β- hTERT variants have a positive relationship with MCPH1/BRIT1 supporting its function as a potent inhibitor of telomerase activity." (PMID 36845691, 2023). "MCPH1 has also been shown to be downregulated in breast, prostate and ovarian cancers, and mutated in 1/10 breast and 5/41 endometrial tumors, suggesting that it could also function as a tumor suppressor (TS) gene." (PMID 23472065, 2013). "In fact, BRIT1/MCPH1 act as a negative regulator of the active isoform of hTERT and its expression is reduced in epithelial ovarian cancer (EOC) samples." (PMID 37514027, 2023). "This work complements studies which have identified decreased MCPH1/BRIT1 DNA copy number and mRNA levels in 40% (35/87) and 63% (19/30) of ovarian cancer respectively." (PMID 36845691, 2023). "Previously we have reported reduced MCPH1/BRIT1 staining in 19% (7/36) of primary ovarian cancer cells cultured from ascites samples." (PMID 36845691, 2023). "Mcph1 was proposed as a potential tumour suppressor because decreased levels of Mcph1 were detected in several types of human cancer including breast and ovarian cancers." (PMID 23516444, 2013). "Similarly, we identified reduced MCPH1/BRIT1 expression in 33% (84/252) of epithelial ovarian cancer tumour samples." (PMID 36845691, 2023). "MCPH1/BRIT1 and the functional form of hTERT were associated negatively which in turn identified MCPH1/BRIT1 as a negative telomerase regulator in primary epithelial ovarian cancer samples." (PMID 36845691, 2023). "Consequently, the expression of MCPH1/BRIT1 could be a useful biomarker in epithelial ovarian cancer." (PMID 36845691, 2023).
prostate carcinoma (8 papers, 2016 to 2025). A carcinoma that arises from epithelial cells of the prostate gland. "A number of pan-cancer studies have reported an association between MCPH1/BRIT1 and prostate cancer." (PMID 36845691, 2023). "The high tumor penetrance in Mcph1 mutant mice is also interesting, which is consistent with the observation that MCPH1 was found to be mutated in many malignancies, including breast, ovarian, and prostate cancer." (PMID 35053391, 2022). "Similarly, deletion of the DNA damage response gene (i.e., MCPH1) is linked with aggressive disease and shorter survival in multiple cancers, including prostate cancer." (PMID 40723280, 2025). "In general, there is a trend toward worse outcomes in patients with MCPH1 deletions, and this is especially seen in bladder, colorectal, and prostate cancers." (PMID 32681070, 2020). "Importantly MCPH1/BRIT1 gene dysregulation has been identified in 12-16% of prostate cancer cases suggesting MCPH1/BRIT1 warrants further study in this cancer type." (PMID 36845691, 2023). "The TSG MCPH1 was deleted in more than 14 % patients in a prostate cancer dataset." (PMID 27556634, 2016). "MCPH1, also downregulated in our clinical CRPC tumor samples, was previously reported to be downregulated in prostate carcinoma." (PMID 36139600, 2022). "Similarly, MCPH1 and MINPP1 exhibited frequent CNLs in the same prostate cancer cohort with PTEN." (PMID 27929028, 2016).
Infertility (5 papers, 2010 to 2022). "Strikingly, infertility has been observed in several Mcph1-deficient mouse models, which is accompanied by atrophy of gonads, i.e., testes and ovaries, as well as tumorigenesis in these organs." (PMID 35053391, 2022). "In addition to its function in mitotic recombination, the infertility induced by MCPH1 deficiency indicates an extended role of MCPH1 in meiotic recombination." (PMID 32735676, 2020). "MCPH1 conditional knockout mice exhibit growth retardation, infertility and reduced brain size, recapitulating phenotypes of human patients." (PMID 32735676, 2020). "One possible explanation is that defective DNA damage repair (as judged by a high level of p-Chk1 and γH2AX shown in Mcph1-Δe8 MEFs) may contribute to infertility phenotypes in Mcph1-Δe8 testes and ovaries." (PMID 36078123, 2022). "Despite consistent phenotypes of impaired gonad development, infertility, and tumorigenesis in various MCPH1 mouse models, MPCH1 patients have not yet been reported for these symptoms." (PMID 35053391, 2022).
premature chromosome condensation syndrome (5 papers, 2013 to 2024). "Mutations in MCPH1/BRIT1 were also found to cause premature chromosome condensation syndrome (PCC) in which cells demonstrate deregulation chromosome condensation." (PMID 36845691, 2023). "Mutations in the MCPH1 gene have been observed previously in MCPH, PCC syndrome and a few cancers." (PMID 23472065, 2013). "The MCPH1/BRIT1 gene is the first gene reported to be responsible for MCPH type 1 (MCPH1, OMIM251200) and also for another syndrome called premature chromosome condensation syndrome (PCC, OMIM 606858), because MCPH1 patient cells exhibit prophase-like and premature chromosome condensation." (PMID 33542216, 2021).
autism (4 papers, 2015 to 2025). Persistent deficits in social interaction and communication and interaction as well as a markedly restricted repertoire of activity and interest as well as repetitive patterns of behavior. "The researchers suggested an association of epilepsy and autism with loss-of-function MCPH1 gene." (PMID 35327368, 2022). "Interestingly, the contribution of the CSMD1 and MCPH1 genes to the formation of autism was also noted when these genes were involved in the duplication region." (PMID 35327368, 2022). "Some researchers propose that DLGAP2, MCPH1 and NEF3 are the candidate genes for autism." (PMID 40790240, 2025).
breast tumors (4 papers, 2010 to 2023). "Loss of heterozygosity (LOH) analysis at the MCPH1 locus demonstrated that the wild-type allele was lost in 40% (8/20) of the studied c.904_916del carrier breast tumors." (PMID 26820313, 2016). "A 38 bp homozygous deletion in MCPH1 was also reported in 1/10 breast tumors." (PMID 23472065, 2013).
cervical cancer (3 papers, 2023 to 2024). A primary or metastatic malignant neoplasm involving the cervix. "Additionally, the MCPH1 gene acts as a repressor of hTERT, mediating the DNA damage response and maintaining chromosomal integrity, and its downregulated expression is linked to the occurrence of cervical cancer." (PMID 39596516, 2024). "An investigation of MCPH1/BRIT1 in cervical cancer demonstrated decreased expression of MCPH1/BRIT1 in 61.3% (19/31) of cases at the mRNA level and 69.8% (44/63) at the protein level in cervical tumour tissues compared to non-tumour tissues." (PMID 36845691, 2023).
colon cancer (3 papers, 2019 to 2021). "In colon cancer cell models, knockdown of E2F1 was correlated with loss of RAD51 expression and RAD51-dependent DSB repair; furthermore, E2F1 and BRIT1 (MCPH1) were shown to form a complex that activates the transcription of BRCA1, CHK1, p73 and CASP7." (PMID 34208195, 2021). "In the YUMC-C1 and YUMC-C2 drug-resistant and metastatic colon cancer cells, respectively, metastatic genes (CDH2, KRAS, CDC42, MCPH1, SRGAP) and markers of stemness (BRACA1 and 2, CD44, KRT5, WNT4, CD29, SAL4) were markedly enhanced." (PMID 33050525, 2020).
lymphoma (3 papers, 2020 to 2023). A malignant (clonal) proliferation of B- lymphocytes or T- lymphocytes which involves the lymph nodes, bone marrow and/or extranodal sites. "Interestingly, Mcph1-Δ and Mcph1-ΔBR1 develop a very high incidence of tumours, yet only in ovaries, in great contrast to 17.1% Mcph1-ko mice, which developed malignant tumours originated from lymphomas and granulosa ovary tumours." (PMID 33542216, 2021).
brain tumors (2 papers, 2016 to 2023). "MCPH1/BRIT1 promoter methylation was also significantly associated with high tumour grade suggesting it could be an epimarker in the detection of brain tumours." (PMID 36845691, 2023). "MCPH1/BRIT1 promoter methylation was identified in 96.6% (28/30) of brain tumour samples." (PMID 36845691, 2023). "In a follow up study MCPH1/BRIT1 promoter methylation was determined in 14 paired circulating cell-free DNA (cfDNA) from serum samples and genomic DNA from tumour tissue also 18 isolated serum samples with different grades of brain tumours." (PMID 36845691, 2023).
chronic myeloid leukemia (2 papers, 2014 to 2023). "In agreement with the key role of MCPH1/BRIT1 in the regulation of cell cycle progression at the G2/M checkpoint, they found that chronic myeloid leukemia cells have a low level of MCPH1/BRIT1 and a defective G2/M arrest, confirming the genomic instability of these cells." (PMID 36845691, 2023).
female infertility (2 papers, 2010 to 2021). Diminished or absent ability of a female to achieve conception. "When examining female infertility, we failed to observe the ovary macroscopically in 2-month-old females of both Mcph1-ΔBR1 and Mcph1-Δ mice." (PMID 33542216, 2021).
gastric adenocarcinoma (2 papers, 2016 to 2023). "Low MCPH1/BRIT1 expression in cervical squamous cell carcinoma, oesophageal squamous cell carcinoma, head-neck squamous cell carcinoma, renal clear cell carcinoma, rectal adenocarcinoma, stomach adenocarcinoma, thymoma and uterine corpus endometroid cancer predicted reduced OS." (PMID 36845691, 2023).